EYA2 (EYA transcriptional coactivator and phosphatase 2)
Description:
Functions both as protein phosphatase and as transcriptional coactivator for SIX1, and probably also for SIX2, SIX4 and SIX5. Tyrosine phosphatase that dephosphorylates 'Tyr-142' of histone H2AX (H2AXY142ph) and promotes efficient DNA repair via the recruitment of DNA repair complexes containing MDC1. 'Tyr-142' phosphorylation of histone H2AX plays a central role in DNA repair and acts as a mark that distinguishes between apoptotic and repair responses to genotoxic stress. Its function as histone phosphatase may contribute to its function in transcription regulation during organogenesis. Plays an important role in hypaxial muscle development together with SIX1 and DACH2; in this it is functionally redundant with EYA1.
Synonyms: EAB1
Tractability: Small molecule: a structure with a bound ligand is known; a high-quality ligand is known; it has a binding pocket of medium quality. PROTAC: ubiquitination databases record sites on it; a small molecule that binds it is known.
Target class: Enzyme
Gene: Protein-coding gene on chromosome 20 (46,894,587 to 47,188,844, forward strand). Ensembl gene ENSG00000064655.
Subcellular location: Cytoplasm; Nucleus
Subcellular location (Human Protein Atlas): Cytosol
Pathways (Reactome):
DNA Repair: Recruitment and ATM-mediated phosphorylation of repair and signaling proteins at DNA double strand breaks
Gene Ontology:
Molecular function: histone H2AXY142 phosphatase activity; magnesium ion binding; protein binding; protein tyrosine phosphatase activity
Biological process: cell differentiation; mesodermal cell fate specification; negative regulation of extrinsic apoptotic signaling pathway in absence of ligand; positive regulation of DNA repair; chromatin remodeling
Cellular component: cytoplasm; cytosol; nucleus; nucleoplasm
Genetic constraint (gnomAD): Loss-of-function variants: 28 observed, 59.32 expected, observed/expected ratio (o/e) 0.47, 90% interval 0.35 to 0.65. The upper end of that interval is the gene's LOEUF score, 0.65, which puts it in group 2 of 6, group 1 being the genes least tolerant of losing a copy. Missense variants: 550 observed, 632.22 expected, observed/expected ratio (o/e) 0.87, 90% interval 0.81 to 0.93. Synonymous variants: 229 observed, 254.73 expected, observed/expected ratio (o/e) 0.9, 90% interval 0.81 to 1.
Homologues: Orthologues: chimpanzee EYA2 (99% identical), macaque EYA2 (97% identical), dog EYA2 (93% identical), pig EYA2 (92% identical), guinea pig EYA2 (88% identical), mouse Eya2 (88% identical), rat Eya2 (88% identical), tropical clawed frog eya2 (79% identical), rabbit EYA2 (73% identical), zebrafish eya2 (59% identical), Drosophila melanogaster eya (44% identical), Caenorhabditis elegans eya-1 (23% identical). Paralogues in human: EYA1 (65% identical), EYA4 (60% identical), EYA3 (46% identical).
Diseases named in the same sentence as EYA2 in open-access papers:
EYA2 is named in the same sentence as 46 diseases in open-access papers, as found by Europe PMC text mining. Sharing a sentence is not in itself a finding about the gene and the disease. The quoted sentences say what the papers report.
breast carcinoma (20 papers, 2012 to 2024). "Our results indicated that EYA2 was closely associated with tumor grade and molecular subtypes of breast cancer." (PMID 30761270, 2019). "Clinically, miR-338-3p expression negatively correlates with the expression of EGFR and EYA2, and low miR-338-3p levels and high EYA2 levels associate with breast cancer lung metastasis." (PMID 28703807, 2017). "EYA2 is over-expressed in breast cancers and is associated with increased metastasis and a poorer outcome." (PMID 22545090, 2012). "Our results indicated that EYA2 was inversely associated with DACH1 in breast cancer." (PMID 30761270, 2019). "The transcription cofactor Eya2 was upregulated in breast cancer patients and miR-30a-5p suppression was attributed to targeting of Eya2." (PMID 37569466, 2023). "miR-338 and miR-30a are EYA2 regulators, and their downregulation increases EYA2 expression in breast cancer, and its reduction and epidermal growth factor receptor (EGFR) downregulation have been associated with lung metastasis." (PMID 35087589, 2022). "Our published work identifies c-Abl and EYA2 as the corresponding kinase and phosphatase that directly control the phosphorylation status of this molecular switch in human breast cancer cells." (PMID 33898441, 2021). "In this report we used TCGA methylation data to analyze EYA2 methylation status of pan-cancer, in which we found EYA2 was hypermethylated in breast cancer than adjacent tissues." (PMID 34044846, 2021). "EYA2 promoted breast cancer cellular proliferation and distant metastasis as the downstream of EGFR." (PMID 32550045, 2020). "Contrary to DACH1, EYA2 facilitates proliferation, migration, invasion, and metastasis of breast cancer cells." (PMID 32550045, 2020). "Survival analyses demonstrated that DACH1 was a favorable factor while EYA2 and SIX1 were risk factors for breast cancer patients." (PMID 32550045, 2020). "In the meanwhile, SIX1 was remarkably upregulated in breast cancers while EYA2 level was increased in Basal-like and Her-2 enriched subtypes." (PMID 32550045, 2020). "An increasing body of evidence demonstrates that Eya2 functions as a cancer related protein in a range of human cancers including ovarian cancer, breast cancer, astrocytoma, and lung cancer." (PMID 31317026, 2019). "In our study, we showed that EYA2 was associated with CSCs markers YBX1, KLF5, and SOX10 in breast tumor tissues, and EYA2 overexpression up-regulated YBX1 in breast cancer cell lines." (PMID 30761270, 2019). "Surprisingly, our analysis of GEO datasets showed that EYA2 mRNA was dramatically lower in breast cancer tissues than normal breast." (PMID 30761270, 2019). "Clone-forming assay and EdU experiment showed that EYA2 overexpression enhanced proliferation of breast cancer cells." (PMID 30761270, 2019). "DACH1 was reported to be an anti-tumor protein in breast cancer, while EYA2 served as a tumor-driving molecule in breast carcinoma." (PMID 30761270, 2019). "In conclusion, EYA2 was significantly correlated with clinico-pathological features of breast cancer, including tumor differentiation and the status of ER, PR, and HER2, and it was enriched in TNBC tumors." (PMID 30761270, 2019). "Our results showed that EYA2 mRNA was higher in grade 3 breast tumors than grade 1–2 cancer, indicating that EYA2 was correlated with poor-differentiation in breast carcinoma." (PMID 30761270, 2019). "We further evaluated the EYA2 mRNA expression in the Cancer Genome Atlas breast cancer dataset downloaded from UCSC Xena." (PMID 30761270, 2019). "Previous studies elaborated that EYA2 drove the proliferation in multiple cancer types, including breast cancer, lung cancer, and astrocytoma." (PMID 30761270, 2019). "miR-338-3p inhibition or EYA2 knockdown greatly attenuated the ability of EGFR to enhance breast cancer cell migration and invasion." (PMID 28703807, 2017). "Taken together, these data suggest that EGFR increases breast cancer cell proliferation through the miR-338-3p/EYA2 pathway." (PMID 28703807, 2017).
breast carcinoma (continued). "Taken together, these data suggest that miR-338-3p represses EYA2 expression by directly targeting its 3′-UTR in breast cancer cells." (PMID 28703807, 2017). "Cell proliferation assays revealed that EGFR overexpression or miR-338-3p inhibition increased breast cancer cell growth, while EYA2 knockdown decreased breast cancer cell growth." (PMID 28703807, 2017). "Overexpression of EYA2 has been observed in epithelial ovarian cancer, lung adenocarcinoma and breast cancer; silencing of EYA2 gene expression has been observed in colorectal cancer and pancreatic cancer." (PMID 28713571, 2016). "Overexpression of EYA2 has been shown to promote epithelial ovarian tumor growth and breast cancer metastases." (PMID 24810906, 2014). "In previous studies we have shown that the tyrosine phosphatase activity of Eya3 and Eya2 promotes single cell motility in breast cancer cells." (PMID 22545090, 2012). "EYA2 is also involved in promoting breast cancer proliferation." (PMID 36371461, 2022). "Generally, both EYA2 and SIX1 were risk factors for prognosis of breast cancer patients." (PMID 32550045, 2020). "As a downstream target of microRNA-30a, EYA2 could boost the proliferation of breast cancer cells through driving G1/S cell cycle progression with up-regulation of cell cycle-related proteins cyclin A, cyclin D1, and cyclin E." (PMID 30761270, 2019). "In addition, EYA2 can also contribute to tumor invasion and metastasis for some cancer types, including breast cancer, lung adenocarcinoma, and astrocytoma." (PMID 30761270, 2019). "EYA2 was majorly detected in the cytoplasm of breast cancer cells." (PMID 30761270, 2019). "Importantly, Kaplan-Meier analysis of public datasets showed that higher EYA2 mRNA level predicted worse prognosis among breast cancer population." (PMID 30761270, 2019). "To explore the biological significance of EYA2 in breast cancer, we conducted data analysis on public breast cancer datasets, and performed immunohistochemistry (IHC) analysis, colony-forming unit assays, EdU assay, western blotting, and immunofluorescence (IF)." (PMID 30761270, 2019). "Our correlation analysis displayed that EYA2 was inversely associated with FOXA1, which further supported the correlation between high EYA2 expression and poor tumor differentiation.ER, PR and HER2 are critical pathological markers in breast cancer." (PMID 30761270, 2019). "Cellular experiments revealed that EYA2 promoted proliferation of breast cancer cell lines." (PMID 30761270, 2019). "Taken together, EYA2 promoted malignant behavior of breast cancer." (PMID 30761270, 2019). "Collectively, EYA2 was closely correlated with clinico-pathological characteristics, and served as a proliferation stimulator for breast cancer cells and an unfavorable prognostic element for breast cancer patients, suggesting that EYA2 is involved in the progression of breast carcinoma." (PMID 30761270, 2019). "Besides, ectopic expression of EYA2 promoted proliferation of breast cancer cells accompanied with the up-regulation of EGFR, cyclin E, and PCNA." (PMID 30761270, 2019). "Importantly, survival analysis indicated that higher EYA2 mRNA level predicted worse overall survival, relapse-free survival and metastasis-free survival among whole enrolled breast cancer patients." (PMID 30761270, 2019). "Furthermore, miR-30a also inhibits breast cancer cell migration through inhibiting Eya2, EYA2, DTL, insulin receptor substrate 2 (IRS2), SEPT7, and Skp2 expression." (PMID 30158978, 2018). "Finally, miR-30a also mediates G1 cell cycle arrest by targeting Eya2, concomitant with decreased c-Myc, cyclin A, cyclin D1, and cyclin E expression in breast cancer." (PMID 30158978, 2018). "In contrast, EYA2 knockdown led to decreased metastatic spread of breast cancer cells to the lung." (PMID 28703807, 2017).
breast carcinoma (continued). "We confirmed the specificity of the EGFR and EYA2 antibodies by IHC of breast cancer tissues or immunoblot with cell lysates and that of miR-338-3p staining by correlation analysis of different miR-338-3p expression in breast tissues examined by hybridization and quantitative RT-PCR, respectively." (PMID 28703807, 2017). "Moreover, low miR-338-3p expression and high EYA2 expression in primary breast cancer correlated with lung metastasis." (PMID 28703807, 2017). "miR-338-3p and EYA2 predict lung metastasis when expressed in primary breast cancers." (PMID 28703807, 2017). "In addition, we showed that EGFR inhibits the expression of miR-338-3p and decreases that of EYA2 in cultured breast cancer cells." (PMID 28703807, 2017). "EYA2 was required to mediate the pro-metastatic functions of Six1 in breast cancer." (PMID 29340020, 2017). "Importantly, miR-338-3p inhibition or EYA2 knockdown greatly attenuated the ability of EGFR to regulate breast cancer cell proliferation." (PMID 28703807, 2017). "However, several studies reported that EYA2 promoted the progression of breast cancer." (PMID 34044846, 2021). "This brings the complexity of cancer research, suggesting the methylation of EYA2 may not be the main cause modification of breast cancer progression to a great extent." (PMID 34044846, 2021). "However, previous study indicated that EYA2 protein abundance increased in breast cancer tissues." (PMID 30761270, 2019). "However, the role of EYA2 in breast cancer remains to be further explored." (PMID 30761270, 2019). "In breast cancer patients, miR-338-3p expression negatively correlates with the expression of EGFR and EYA2, EGFR status positively associates with EYA2 expression, and miR-338-3p and EYA2 predict breast cancer lung metastasis when expressed in primary breast cancers." (PMID 28703807, 2017). "Furthermore, overexpression of miR-338-3p reversed the stimulatory effect of EGFR on breast cancer cell proliferation, and the inhibitory effect of miR-338-3p on breast cancer cell proliferation could be rescued by EYA2 overexpression." (PMID 28703807, 2017). "Interestingly, EYA2 has recently been reported to influence TGF beta signaling in breast cancer cells, but in contrast to our findings in pancreatic cancer, these authors found that EYA2 functioned as a promoter of growth and metastases and a potential therapeutic target for inhibition." (PMID 24810906, 2014). "One approach has already been demonstrated in a breast cancer model where a small molecule inhibited the interaction between SIX1 and EYA2, reducing downstream TGF-β signaling and EMT leading to reduced metastasis in mouse xenografts." (PMID 34490256, 2021). "Remarkable relation among EYA1, EYA2 and EYA3 genes with the LumB subtype are in accordance with the previous finding that EYA genes play an important role in breast cancer growth and metastasis as well as directing cells to the repair pathway upon DNA damage." (PMID 34112093, 2021). "Other targets of miR-30a in breast cancer have also been identified as potential links between this miRNA and the regulation of metastatic progression, including vimentin, MTDH, and Eya2." (PMID 32309442, 2020). "The following survival analyses showed DACH1, EYA2, and SIX1 were predictive biomarkers of prognosis of breast cancer patients." (PMID 32550045, 2020). "Western blotting showed that EYA2 overexpression induced the up-regulation of YBX1, EGFR, cyclin E, and PCNA in both these two breast cancer cell lines." (PMID 30761270, 2019). "Eya2 is reported to cooperate with Six1 to promote metastasis via the induction of TGF-β and epithelial-mesenchymal transition (EMT) in breast cancer cells." (PMID 31317026, 2019). "In agreement with our finding, knockdown of EYA2 antagonized the SIX1-induced TGF-β signaling, and partially restored epithelial properties with a decrease of the mesenchymal marker fibronectin in breast cancer MCF-7 cells." (PMID 30761270, 2019).
breast carcinoma (continued). "Cellular IF assay also showed that EYA2 overexpression enhanced the protein abundance of YBX1, EGFR, and PCNA in both breast cancer cell lines." (PMID 30761270, 2019). "Taken together, these results suggest that EGFR increases breast cancer cell migration and invasion as well as EMT through the miR-338-3p/EYA2 pathway." (PMID 28703807, 2017). "Through the miR-338-3p/EYA2 pathway, EGFR increases breast cancer cell growth, epithelial-to-mesenchymal transition, migration, invasion and lung metastasis in vitro and in a allograft tumor mouse model in vivo." (PMID 28703807, 2017). "We assessed EGFR and EYA2 expression by immunohistochemical staining (IHC) and miR-338-3p expression by miRNA in situ hybridization (MISH) in 95 human breast cancer samples." (PMID 28703807, 2017). "For example, EYA2 can form a complex with SIX1 to regulate epithelial-mesenchymal transition by the activation of TGF-β pathway, consequently promoting the metastasis of breast cancer cells." (PMID 34044846, 2021). "Besides, decreased DACH1 and increased EYA2 and SIX1 heralded the poor prognosis of breast cancer patients." (PMID 32550045, 2020). "We also assessed the mRNA level of EYA2 in distinct breast cancer cell types, showing that there was no remarkable difference of EYA2 mRNA between luminal-type and basal-like cell lines (p = 0.666)." (PMID 30761270, 2019). "Indeed, miR-338-3p mimics inhibited EYA2 expression in ZR75-1, MCF-7 and MDA-MB-231 human breast cancer cells and 4T1 mouse cancer cells." (PMID 28703807, 2017). "Moreover, we demonstrated that, through EYA2 inhibition, miR-338-3p not only suppressed breast cancer cell proliferation, EMT, migration and invasion in vitro, but also prevented breast cancer cell metastasis to lung in vivo." (PMID 28703807, 2017). "Next, we determined whether EGFR promotes breast cancer cell migration, invasion and EMT via the miR-338-3p/EYA2 axis." (PMID 28703807, 2017). "It is reported that knockdown Eya2 deletion in breast carcinoma cells inversed Six1 ability to facilitate TGF-β pathway, as well as to promote properties correlated with EMT and CSCs, proposing that Six1-dependentm Eya2 process to regulate a variety of pro-metastatic features." (PMID 38372877, 2024). "Furthermore, miR-338-3p overexpression reversed the stimulatory effect of EGFR on breast cancer cell migration and invasion as well as EMT, and the inhibitory effect of miR-338-3p on these phenotypes could be rescued by EYA2 overexpression." (PMID 28703807, 2017). "However, the role of EYA2 in breast cancer is still lack of full understanding." (PMID 30761270, 2019).